NRG1 (neuregulin 1)
Diseases named in the same sentence as NRG1 in open-access papers (continued):
Sharing a sentence is not in itself a finding about the gene and the disease.
infection (continued). "Infection of C57BL/6 mice with Plasmodium berghei ANKA (PbA) upregulated NRG-1 mRNA in the brain cortex suggesting that NRG-1 expression may be protective against PbA-induced damage in the brain." (PMID 29636063, 2018). "Consistently, as suggested from the quantification of NS5A positive cells two weeks after infection, neutralization of NRG1 as well as inhibition of Akt or a combination of both substantially reduces the number of NS5A-expressing cells, when compared to respective IgG isotype or DMSO controls." (PMID 26886748, 2016). "Additionally, Nup98, Nrg1, and erbB4 were all upregulated in the murine myocardium during acute/early phase of CVB3 infection, and Nrg-1 and erbB4 were downregulated at a later phase of infection, suggesting a cardioprotective role of this signal cascade in cellular response to infection." (PMID 31396490, 2019). "Here we found that genes IRS2, NRG1, HBEGF, and EREG regulating AKT signaling are downregulated in M-MDSC isolated from CoV2+ participants long after recovery from infection." (PMID 35812392, 2022). "After an initial decline, the CFU of the t-EED1 + yeast stabilized and increased in liver and spleen while they continuously declined after infection with the WT, t-EED1- or tet-NRG1 yeast or hypha." (PMID 34162849, 2021). "Because C. albicans encounters a variety of host microenvironments during infection, our results suggest that UME6 and NRG1 expression can be differentially modulated by multiple signaling pathways to control filamentation and virulence in vivo." (PMID 25811669, 2015). "To test the role of DISC1 on NRG1-ErbB4 signalling, we then used lentiviral infection to express control or DISC1 shRNA in primary neuron cultures, followed by NRG1 treatment." (PMID 26656849, 2015). "Some of these expression patterns (e.g. AGP2, NRG1) reflected the yeast cell growth of eed1Δ at the 12 h time point and were similar to the expression pattern monitored during the RHE infection." (PMID 21512583, 2011). "In contrast, constitutive expression of NRG1 blocks in vitro and in vivo filamentation and prevents the development of disease, but not organ infection, in a mouse model of disseminated infection." (PMID 38376205, 2024). "Neutrophils have not been previously documented as being sources of NRG-1 therefore, to confirm this observation, we performed flow cytometry on BMNCs over the course of infection and examined NRG-1 expression." (PMID 39095837, 2024). "The interaction between NRG1 and its tyrosine kinase receptor, epidermal growth factor ERBB4, has also been shown to be beneficial in promoting cardioprotective effects post-ischemia as well as being involved in host cell response to infection." (PMID 31396490, 2019). "Overall, because C. albicans encounters a variety of microenvironments during infection that can promote or inhibit filamentation, our results suggest that UME6 and NRG1 transcripts can be differentially modulated by multiple signaling pathways which respond to host environmental cues." (PMID 25811669, 2015). "albicans genetically restricted to the yeast form byconstitutive expression of NRG1 are able to establish infection inmice but no disease results until the expression of NRG1 isrepressed and the organism is able to form filaments." (PMID 22103005, 2011). "Among these are the hyphal growth repressor gene NRG1, which was 2.4-fold up-regulated in eed1Δ 24 h after infection and the amino acid permease gene AGP2 which is up-regulated in eed1Δ 12 and 24 h after infection." (PMID 21512583, 2011). "While it did not return GLT-1 expression to baseline uninfected levels, administration of exogenous NRG-1 treatment significantly rescued infection-induced downregulation of GLT-1, with fewer GLT-1 negative patches and more uniform expression seen in the tissue following treatment." (PMID 39095837, 2024).
infection (continued). "Expression of NRG-1 by CBNeuts reveals a distinct brain-specific phenotypic and transcriptomic profile of these cells which also display functional heterogeneity based on age and integrin expression, and NRG-1/ErbB4 signaling play a role in limiting infection-induced neuropathology." (PMID 39095837, 2024). "They include LbCon7 (JGI ID# 292045), a C2H2 Zn-finger TF homologous to Con7p, the central regulator of infection-related morphogenesis in the rice blast fungus Magnaporthe grisea and LbNrg1 (JGI ID# 296037), the homolog of the carbon catabolite Zn-finger repressor Nrg1 from Cryptococcus." (PMID 28923004, 2017). "Strikingly, deletion of NRG1 in 78048 reduced filamentation in vivo, expression of candidalysin (ECE1), and virulence without dramatically altering establishment of infection." (PMID 38376205, 2024).
neurological disorders (12 papers, 2016 to 2025). "Neuregulin 1 (NRG-1) is a key neurotrophic factor involved in energy homeostasis and CNS development, and impaired NRG-1 signaling is associated with neurological disorders." (PMID 27057274, 2016). "Moreover, exploring additional pathways associated with NRG1 and investigating its relevance to other neurological disorders are crucial areas for future research." (PMID 38331905, 2024). "Neuregulin 1 is involved in the process of a series of neurological diseases." (PMID 33274218, 2020). "Taken together, NRG1 plays a critical role in the central nervous system based on its gene–dosage balance, and abnormal levels or activity of NRG1 could potentially contribute to the pathogenesis of relevant neurological disorders." (PMID 33854034, 2021).
adenocarcinoma (11 papers, 2013 to 2025). A common cancer characterized by the presence of malignant glandular cells. "The causal change is an NRG1 fusion (e.g., CD74–NRG1), a rare event enriched in KRAS-wild-type, often mucinous, adenocarcinoma." (PMID 41154602, 2025). "Clinically, all NRG1 fusion tumors were adenocarcinomas, with the majority registered as female (7/8, 87.5%)." (PMID 38173003, 2024). "The patient harbouring the NRG1 amplification (patient #3772) was a 76-year-old woman with poorly differentiated adenocarcinoma, who demonstrated progression after three cycles of cetuximab/irinotecan." (PMID 31653970, 2019). "Increased expression of ErbB receptors or ligands, such as transforming growth factor-α (TGFα), amphiregulin (AREG), neuregulin-1 (NRG1), and cripto-1 (TDGF-1), are associated with mammary hyperplasia and adenocarcinoma development." (PMID 23383347, 2013). "Notably, tumors harboring an NRG1 fusion all presented histologically as adenocarcinomas and occurred primarily in female patients with only one male patient, thereby exhibiting a female predominance." (PMID 38173003, 2024). "All NGS NRG1 fusion tumors were adenocarcinomas, with a higher prevalence in females." (PMID 38173003, 2024). "Multiparous transgenic female mice expressing NRG1, a ligand for ERBB3 and ERBB4, under control of the MMTV promoter also develop adenocarcinomas in the mammary glands at a median age of 12 months, suggesting ErbB4 to be contributing to neuregulin-induced carcinogenesis." (PMID 25516216, 2014).
neurodegenerative disease (11 papers, 2017 to 2025). A disorder of the central nervous system characterized by gradual and progressive loss of neural tissue and neurologic function. "Non-coding RNAs, including lncRNAs and miRNAs, can both positively and negatively, directly and indirectly, influence protein expression, such as NRG1, positioning them as key players in the pathogenesis of neurodegenerative diseases, including MS." (PMID 40192890, 2025). "NRG1 also helps maintain the functional integrity and survival of peripheral nerve axons and therefore NRG1/ErbB signaling has also been considered a potential therapeutic target in neurodevelopmental and neurodegenerative diseases." (PMID 36997967, 2023). "Experimental studies indicate that plasma NRG1 levels are reduced in nervous system disorders and neurodegenerative diseases." (PMID 35625715, 2022). "These properties point to the NRG1-ErbB system as a potential target of interest for the treatment of MN degenerative diseases." (PMID 29375317, 2017). "Thus, the precise role of NRG1-ErbB signaling in neurodegenerative diseases remains largely undefined." (PMID 41373580, 2025). "Although research has demonstrated that NRG1 can promote axonal regeneration and play a neuroprotective role in neurodegenerative diseases, it remains unclear about the biological functions and related mechanisms of NRG2 in neurodegenerative diseases, especially in AD." (PMID 33897409, 2021). "As far as we know, the mRNA levels of NRG1 and ErbB4 have not been investigated during CCH, but similar changes have been reported in other animal models of neurodegenerative diseases." (PMID 29875654, 2018).
heart disease (9 papers, 2012 to 2025). "NRG1 has therapeutic effects on many forms of heart disease by directly acting on cardiomyocytes, endothelial cells, macrophages, and fibroblasts to promote cell proliferation, anti-apoptosis, anti-inflammatory and antioxidant effects, and regulate myocardial energy metabolism." (PMID 36120374, 2022). "Activating either NRG1 or ErbB2/4 improved CM proliferation, suggesting that the NRG1/Erb signaling pathway is conserved and thus might serve as an effective therapeutic strategy for heart diseases." (PMID 35898398, 2022). "The roles of NRG1 in cardiac diseases are however controversial." (PMID 22792252, 2012). "Hence, Nrg-1 plays a protective role in animal models of heart disease." (PMID 23894340, 2013).
neurodevelopmental disorder (9 papers, 2011 to 2024). A behavioral and cognitive disorder with onset during the developmental period that involves impaired or aberrant development of intellectual, motor, or social functions. "This is interesting considering the increased expression of disease-associated genes in neurodevelopmental disorders during fetal development and high NRG1 expression at ages with highest risk for Scz onset." (PMID 29264769, 2018). "Moreover, RET and NRG1 double mutation zebrafish embryos showed the most severe neurodevelopmental disorders compared to single mutation and control sibling embryos." (PMID 37484916, 2023). "This highlights the potential significance of our findings for understanding the long-term impact of prenatal morphine exposure on brain development and the potential contribution of NRG1 signaling alterations to the pathogenesis of neurodevelopmental disorders." (PMID 39109071, 2024). "In theory, therefore, these findings would seem to suggest that NRG1 and ErbB4 could be promising targets for gene therapy of neurodevelopmental disorders such as Sz." (PMID 32546684, 2020). "Further research is warranted to elucidate the precise mechanisms involved and explore potential therapies targeting the NRG1/ErbB4 pathway, which could mitigate the adverse effects of prenatal morphine exposure and lead to novel therapeutic strategies for neurodevelopmental disorders." (PMID 39109071, 2024). "Given NRG1's established role in modulating inflammatory processes, these alterations could have significant implications for understanding the long-term effects of prenatal morphine exposure on brain development, particularly in the context of neurodevelopmental disorders." (PMID 39109071, 2024).
brain disorder (8 papers, 2013 to 2023). A disease affecting the brain or part of the brain. "Accordingly, impaired NRG1/ErbB4 signal is thought to underlie NMDA receptor dysfunction found in brain diseases such as schizophrenia." (PMID 23408472, 2013). "Here, we discuss the findings revealed by Nrg1-reporting mice and their relevance to physiology and brain disorders." (PMID 37147705, 2023). "The potential contribution of virus-derived cytokines (virokines) that mimic EGF and neuregulin-1 in brain diseases are also discussed." (PMID 23408472, 2013). "Indeed, NRG1 levels are increased in postmortem brain tissues of patients with brain disorders." (PMID 33854034, 2021).
cardiovascular diseases (7 papers, 2008 to 2025). "Importantly, DOX-induced cardiovascular disease has been shown to be associated with NRG1/ErbB pathway inhibition." (PMID 39742014, 2024). "Here, we summarize recent research advances on the molecular mechanisms of NRG1, elucidate the contribution of NRG1 to cardiovascular disease, discuss therapeutic approaches targeting NRG1 associated with cardiovascular disease, and highlight areas for future research." (PMID 36120374, 2022). "These emerging technologies can accelerate the development of NRG1 therapy for cardiovascular diseases." (PMID 36120374, 2022). "In this section, we summarize the physiological and pathological roles of NRG1 in cellular and cardiovascular tissues to fully illustrate the important role of NRG1 in the development of cardiovascular diseases." (PMID 36120374, 2022). "GGF2 is a full-length splice variant of the NRG-1 gene (also known as cimaglermin alfa or NRG-1β3), which has been investigated as a novel therapeutic strategy for cardiovascular diseases." (PMID 30971932, 2019). "We summarize the role of NRG1 in cardiovascular diseases in conjunction with the related pathways." (PMID 36120374, 2022). "Studies using NRG1 for cardiovascular regeneration and repair have focused on exogenous administration, and in vivo and in vitro experiments have confirmed its clinical effectiveness, respectively, and its greater potential and clinical value in the treatment of cardiovascular disease." (PMID 36120374, 2022).
colorectal (4 papers, 2016 to 2024). "Here, we performed a detailed time-course expression analysis of several NRG1 isoforms and ErbB receptors in the rat superficial digitorum flexor muscle after three types of median nerve injuries of different severities." (PMID 29568012, 2018). "A time-course mRNA expression analysis of the NRG1 isoforms, ErbB3 and ErbB4 receptors, and their co-receptors ErbB2 and ErbB1, was performed on SDF muscle after median nerve injury." (PMID 29568012, 2018).
peripheral neuropathy (2 papers, 2022 to 2025). A disorder affecting the peripheral nervous system. "Importantly, The TCM compound Jinmaitong improved the phenotype of peripheral neuropathy by regulating the gut microbiota composition and increasing the levels of neuregulin 1 (NRG1) in DPN rats." (PMID 35242721, 2022).
animal disease (1 paper, 2019). "Because the current study was conducted in cultured neurons, further study is needed to clarify the effects of NRG1 on related animal disease models." (PMID 30328584, 2019).
hematologic malignancies (1 paper, 2025). "Other experimental potential biomarkers that are being tested in patients with hematologic malignancies are high-sensitivity CRP (Hs-CRP), interleukin-6 (IL-6), myeloperoxidase (MPO), fatty-acid-binding protein (FABP), glycogen-phosphorylase-binding protein (GPBP) and neuregulin-1 (NRG-1)." (PMID 39941907, 2025).
inflammation (1 paper, 2025). Aberrant reaction of the microcirculation characterized by movement of fluid and leukocytes from the blood into extravascular tissues. "The effect of NRG1 on pulp inflammation and mineralization was assessed." (PMID 40580029, 2025).
neuromuscular disease (1 paper, 2025). "These detrimental outcomes should be carefully considered when developing therapeutic strategies involving NRG1 for the treatment of neuromuscular diseases." (PMID 41373580, 2025).
retinopathy (1 paper, 2019). "The results of these experiments indicate that NRG1 improves retinal function and inhibits retinopathy in db/db mice." (PMID 30832367, 2019).
NRG1 also shares sentences with these, for which no sentence is quoted: asthma (3 papers); autism spectrum disorder (3); metabolic syndrome (3); type 1 diabetes (3); Arrhythmia (2); gallbladder cancer (2); head and neck tumors (2); Intellectual disability (2); intestinal diseases (2); metastatic disease (2); substance abuse (2); Abdominal obesity (1); acinar adenocarcinoma (1); acute myeloid leukemia (1); alcohol abuse (1); allergic rhinitis (1); Allergy (1); aneurysmal bone cyst (1); aortic valve stenosis (1); attention deficit hyperactive disorder (1); autoimmune encephalitis (1); autosomal recessive primary microcephaly (1); B-cell lymphoma (1); behavioral disorder (1); benign prostate hyperplasia (1); Cachexia (1); Candidemia (1); candidiasis (1); cardiac arrest (1); cerebral infarction (1).
A further 79 diseases each share a sentence with NRG1 in 1 paper.